MC4R (melanocortin 4 receptor)
Diseases named in the same sentence as MC4R in open-access papers (continued):
Sharing a sentence is not in itself a finding about the gene and the disease.
non-alcoholic steatohepatitis (7 papers, 2015 to 2026). "We also demonstrated short-term improvement in liver injury, fat metabolism, and fibrosis as well as long-term improvement in fibrosis and reduction in tumorigenesis in melanocortin-4 receptor-deficient (Mc4r-KO) mice, a model of metabolic dysfunction-associated steatohepatitis (MASH)." (PMID 40503100, 2025). "Thus, Mc4r-/- mice on a high-fat diet were proposed as a model of non-alcoholic steatohepatitis, or NASH." (PMID 36793548, 2022). "P3 has a younger brother with the same MC4R mutation who recently had BS at 5 years of age and presented with non-alcoholic steatohepatitis (stage 3–4), a condition not previously seen in P3." (PMID 35095762, 2021).
hepatocellular carcinoma (6 papers, 2015 to 2025). A malignant tumor that arises from hepatocytes. "Our findings with the MC4R-KO mice suggest that SGLT2 inhibitors have a significant clinical impact on human NASH and NASH-associated hepatocellular carcinoma." (PMID 29402900, 2018). "In addition, MC4R-KO mice developed hepatocellular carcinoma when kept on a high-fat diet for up to one year." (PMID 41002740, 2025).
obesity syndrome (5 papers, 2016 to 2026). "While MC4R agonists like setmelanotide have demonstrated efficacy in rare monogenic obesity syndromes involving MC4R mutations, their therapeutic potential for acquired HO remains unexplored." (PMID 41601974, 2026). "MC4R variants are associated with both dominant and recessive monogenic obesity syndrome (OMIM# 618406)." (PMID 39414991, 2025). "As a member of the melanocortin receptor family, melanocortin 4 receptor (MC4R) plays a critical role in regulating energy homeostasis and feeding behavior, and has been proven as a promising therapeutic target for treating severe obesity syndrome." (PMID 35741395, 2022). "Setmelanotide, synthesized as an agonist for MC4R, was approved by the U.S. Food and Drug Administration (FDA) in the United States in November 2020, and in the European Union in July 2021, for alleviating severe obesity syndrome." (PMID 35741395, 2022).
anorexia nervosa (4 papers, 2016 to 2024). A disorder most often seen in adolescent females characterized by a refusal to maintain a minimally normal body weight, an intense fear of gaining weight, a disturbance in body image, and, in postmenarcheal females, the development of amenorrhea. "Variations in AgRP could be due to suppression of MC4-R, leading to a decreased feeding signal and thereby increasing the risk of developing anorexia nervosa." (PMID 26758700, 2016). "We aimed to (i) detect variants in the lipocalin-2 gene (LCN2) which are relevant for body weight regulation and/or anorexia nervosa (AN); (ii) describe and characterize the impact of LCN2 and MC4R variants on circulating lipocalin-2 level." (PMID 37025415, 2023). "Furthermore, the cellular internalization rate of α-MSH/IgG IC by MC4R-expressing cells was decreased in obese but increased in patients with anorexia nervosa." (PMID 30755592, 2019).
binge eating disorder (4 papers, 2020 to 2026). Recurrent episodes of over-eating. "Gain of function variants in MC4R, which have a weight lowering effect, have been associated with binge eating disorder (BED) in overweight subjects." (PMID 32373164, 2020). "Furthermore, meta-analysis confirm that loss-of-function variants in MC4R do not show a connection with binge eating disorder, different from conclusion in a controversial study; however, gain-of-function variants in MC4R are linked to binge eating disorder." (PMID 41596694, 2026).
endometrial cancer (4 papers, 2011 to 2023). Primary or metastatic malignant neoplasm involving the endometrium (mucous membrane that lines the endometrial cavity). "We examined the association of FTO rs9939609 and MC4R rs17782313 with endometrial cancer risk in a pooled analysis of nine case-control studies within the Epidemiology of Endometrial Cancer Consortium (E2C2)." (PMID 21347432, 2011). "Unconditional logistic regression models were used to assess the relation of FTO rs9939609 and MC4R rs17782313 genotypes to the risk of endometrial cancer." (PMID 21347432, 2011). "Description of the studies included in the pooled analysis of FTO rs9939609 and MC4R rs17782313 and endometrial carcinoma risk." (PMID 21347432, 2011). "Association of the FTO rs9939609 and MC4R rs17782313 with endometrial carcinoma risk among women with BMI data available." (PMID 21347432, 2011). "Association of the FTO rs9939609 and MC4R rs17782313 with endometrial carcinoma risk." (PMID 21347432, 2011). "Large-scale data analysis of MC4R also points out that a SNIP close to MC4R gene was related to endometrial cancer and breast cancer." (PMID 37127675, 2023). "The MC4R rs17782313 polymorphism was not related to endometrial cancer risk (per allele OR = 0.98; 95% CI: 0.91–1.06; p = 0.68)." (PMID 21347432, 2011). "Although the power of our MC4R analysis was modest, odds ratios were close to one, providing no suggestion of an association of this SNP with endometrial cancer risk among non-Hispanic white women." (PMID 21347432, 2011). "Thus, we hypothesized a stronger association of the FTO rs9939609 A allele and MC4R rs17782313 C allele and risk of the endometrioid type of endometrial carcinoma than with nonendometrioid types." (PMID 21347432, 2011).
hypertriglyceridemia (4 papers, 2021 to 2025). A laboratory test result indicating elevated triglyceride concentration in the blood. "In a previous follow-up study of adults over the age of 18, those with the A allele (AG + AA) of rs12970134 MC4R had an increased risk of hypertriglyceridemia in the highest consumption group of red meat (p < 0.05)." (PMID 35468744, 2022).
hypothyroidism (4 papers, 2014 to 2025). Abnormally low levels of thyroid hormone. "Both qPCR and in situ hybridization showed hypothyroidism to increase endogenous Mc4r expression in the PVN, whereas hyperthyroidism repressed Mc4r expression in the ARC." (PMID 29997323, 2018). "Thyroid status is also known to specifically regulating Mc4r expression in the PVN, with hypothyroidism increasing endogenous Mc4r expression, which parallels the well-established rise in PVN Trh expression also induced by hypothyroidism." (PMID 25229406, 2014). "This suggests that the homeostatic regulation of the Mc4r gene by thyroid status may be disrupted by prolonged and severe hypothyroidism, compromising the activation of anorexigenic mechanisms (as observed in C57BL/6J mice)." (PMID 39409121, 2024).
mental disorder (4 papers, 2017 to 2023). A disease that has its basis in the disruption of mental process. "Here, three new genes of Cryptochrome (CRY), Melanocortin-4 Receptor (MC4R), and Caveolin (CAV) were associated with mental disorders-related SNPs in GWAS." (PMID 37542261, 2023). "Our study provides evidence that the same genes (e.g., MC4R, FIBIN, and FMO5) harbor both common and rare variants affecting body size and that anthropometric traits share genetic loci with developmental and psychiatric disorders." (PMID 28963451, 2017).
myocardial infarction (4 papers, 2011 to 2026). Gross necrosis of the myocardium, as a result of interruption of the blood supply to the area, as in coronary thrombosis. "Experimental work demonstrates that activation of hypothalamic leptin and melanocortin-4 receptor (MC4R) pathways confers cardioprotection after myocardial infarction, even in the presence of peripheral leptin resistance." (PMID 41596265, 2026).
Prader-Willi syndrome (4 papers, 2015 to 2025). "Previous evaluation included methylation test for Prader-Willi syndrome, thyroid function test, leptin level, melanocortin 4 receptor gene sequencing, cortisol level, bone age, and HbA1c were all normal." (PMID 25927380, 2015).
Stroke (4 papers, 2013 to 2025). Sudden impairment of blood flow to a part of the brain due to occlusion or rupture of an artery to the brain. "We conducted a two-stage study to assess a series of associations between rs17817449 at the FTO and rs6567160 at the MC4R and the risk of stroke events." (PMID 36530622, 2022). "We aimed to assess the associations between rs17817449 at the FTO and rs6567160 at the MC4R and the risk of stroke events in middle-aged and older Chinese people." (PMID 36530622, 2022). "The G allele of rs17817449 at the FTO, not rs6567160 at the MC4R, was associated with a decreased risk of fatal stroke occurrence; its functional role in stroke should be explored in relatively healthy middle-aged to older Chinese people." (PMID 36530622, 2022). "Rs17817449 at FTO, but not rs6567160 at the MC4R, was associated with the risk of fatal all strokes; the genetic loci should be a potential biomarker for stroke events, and its functional role in stroke needs to be explored in relatively healthy middle-aged to older Chinese." (PMID 36530622, 2022). "However, the relationships between the MC4R and the FTO and the risk of a fatal stroke remain largely unknown." (PMID 36530622, 2022). "Like the Mannheim-Heidelberg stroke study in Germany, neither the FTO nor the MC4R was associated with LAA stroke in Han Chinese people." (PMID 36530622, 2022).
atherosclerosis (3 papers, 2016 to 2025). A disease characterized by the build-up of fatty material and calcium deposition in the arterial wall resulting in partial or complete occlusion of the arterial lumen. "In this study, we demonstrated that loss of MC4R exacerbates vascular diseases, such as AAA and atherosclerosis by using Mc4r-deficient mice." (PMID 37957201, 2023). "To explore accessorily whether MC4R deficiency promotes atherosclerosis, we crossed MC4RTB/TB mice with apolipoprotein E (ApoE) knockout (ApoE−/−) mice to generate double-deficient MC4R and ApoE (ApoE−/−;MC4RTB/TB) mice." (PMID 37957201, 2023). "Here, by using melanocortin-4 receptor (MC4R) deficient mice, we confirmed MC4R deficiency promotes AAA and atherosclerosis." (PMID 37957201, 2023). "In comparison to ApoE−/−;MC4R+/+ mice, ApoE−/−;MC4RTB/TB mice exhibited exaggerated atherosclerosis." (PMID 37957201, 2023). "Since the development of atherosclerosis correlated with cholesterol levels one can consider the cause of atherosclerosis found already under cholesterol-free diet as an additive effect of both gene defects rather than as an Mc4r-specific, lipid-unrelated mechanism." (PMID 28030540, 2016).
colorectal cancer (3 papers, 2013 to 2025). A primary or metastatic malignant neoplasm that affects the colon or rectum. "In the subgroup analysis by cancer type, the MC4R rs17782313 SNP was moderately associated with the risk of colorectal cancer (OR = 1.11, 95% CI = 1.03–1.20)." (PMID 32899047, 2020). "Given the limited therapeutic options for ATC and the high recurrence rates in advanced colorectal cancer, targeting MC4R could provide a valuable therapeutic alternative to existing treatments." (PMID 40004697, 2025). "We hypothesized that MC4R inhibition by the melanocortin receptor antagonist ML can reduce tumor proliferation of colorectal cancer cells and of anaplastic thyroid cancer cells and synergize with standard chemotherapy agents." (PMID 40004697, 2025). "Therefore, the objective of our research was to investigate, for the first time, the role of MC4R in anaplastic thyroid cancer and colorectal cancer, and to determine whether it could represent a novel potential molecular target." (PMID 40004697, 2025). "Western blot analysis further validated a marked difference in MC4R protein expression between normal cells, HUVECs, and both ATC and colorectal cancer cells." (PMID 40004697, 2025). "In particular, there is currently no available information about MC4R expression or activity in anaplastic thyroid cancer or colorectal cancer." (PMID 40004697, 2025). "Moreover, HT-29 colorectal cancer cells were also positive for the MC4R protein when comparing the immunofluorescence of proliferating cells to negative controls in the absence of the primary antibody anti-MC4R." (PMID 40004697, 2025).
dilated cardiomyopathy (3 papers, 2017 to 2026). Cardiomyopathy which is characterized by dilation and contractile dysfunction of the left and right ventricles. "In the cardiovascular system, MC4R activation increases heart rate and blood pressure, whereas MC4R deficiency causes dilated cardiomyopathy in mice." (PMID 32785054, 2020). "Mc4r has been shown to be involved in the development of dilated cardiomyopathy." (PMID 41615915, 2026). "We show here that absence of the melanocortin-4 receptor (MC4R) in mice causes dilated cardiomyopathy, characterized by reduced contractility and increased left ventricular diameter." (PMID 28829041, 2017).
epilepsy (3 papers, 2020 to 2025). A brain disorder characterized by episodes of abnormally increased neuronal discharge resulting in transient episodes of sensory or motor neurological dysfunction, or psychic dysfunction. "While much is known about the neuronal alterations following ELS, there remains a significant gap in our understanding of astrocytic responses, their contributions to early-life epilepsy and seizures, and their modulation of the MC4R effect." (PMID 40015967, 2025). "Not only do MC4R-specific agonists improve memory but ACTH-treatment in epileptic KCNA1-null mice demonstrated protection against learning and memory deficits induced by epilepsy." (PMID 32670020, 2020). "However, the role of MC4R activation in mitigating astrocyte dysfunction in epilepsy has not been explored." (PMID 40015967, 2025).
erectile dysfunction (3 papers, 2009 to 2022). Persistent or recurrent inability to achieve or to maintain an erection during sexual activity. "Given MC4R targets several organ systems with various physiologic effects, including possible therapeutic roles in promoting weight loss and treating impotence, there are currently several MC4R agonists entering human clinical testing." (PMID 30629642, 2019). "The obese phenotype of male MC4R-deficient mice is further characterized by erectile dysfunction and changed sexual behavior." (PMID 19309531, 2009). "Obese melanocortin-4-receptor-deficient (MC4R-/-) male mice are reported to have erectile dysfunction, while homozygous MC4R-/- female mice are apparently fertile." (PMID 19309531, 2009). "It will be of interest in future work to examine whether loss of weight by voluntary exercise restores ovarian cycles, as has been shown for erectile dysfunction in male MC4R-deficient mice." (PMID 19309531, 2009). "Bremelanotide (PT-141) is a MC4R agonist approved in June of 2019 by the FDA for erectile dysfunction in men and hypoactivity sexual desire disorder in premenopausal women, as characterized by low sexual desire that causes marked distress or interpersonal difficulty." (PMID 36291616, 2022).
gestational diabetes (3 papers, 2017 to 2024). Carbohydrate intolerance first diagnosed during pregnancy. "We aimed to assess whether the MC4R genotype affected longitudinal changes in body weight and glucose metabolism biomarkers among women with prior gestational diabetes mellitus (GDM)." (PMID 28852042, 2017). "MC4R DNA methylation levels on the maternal and fetal side of placenta normoglycemic (NGT) and gestational diabetes (GDM) women expressed as mean and standard deviation (SD)." (PMID 35571924, 2022).
Hyperphagia (3 papers, 2025). "The recent advancements in understanding hyperphagia have led to the development of Symptoms and Impacts of Hyperphagia Questionnaires that are each tailored for patients with hyperphagia resulting from MC4R pathway–associated diseases, such as BBS." (PMID 39856371, 2025). "The recently developed Symptoms of Hyperphagia and Impacts of Hyperphagia questionnaires were created as part of the CARE‐BBS study to assess the emotional and physical burden of MC4R pathway‐related hyperphagia in patients with BBS and their caregivers." (PMID 40528426, 2025). "Hyperphagia is a severe form of pathologic, insatiable hunger that confers multifaceted burden, with severe consequences experienced across multiple domains (eg, emotions, relationships, work, school) by both patients and caregivers of patients with rare MC4R pathway diseases." (PMID 40560452, 2025). "Hyperphagia has a broad negative effect on patients' quality of life and is considered one of the most distressing symptoms of MC4R pathway diseases." (PMID 40528426, 2025).
ischemic stroke (3 papers, 2015 to 2022). A stroke disorder caused by obstruction of blood flow to the brain, due to thrombotic (local blood clot formation) or embolic (due to a blood clot or other material traveling from another site) event. "Numerous studies have indicated that activation of MC4R exerts anti-inflammatory effects by inhibiting the production of proinflammatory cytokines in various diseases, including circulatory shock, myocardial ischemia, and ischemic stroke." (PMID 29642894, 2018). "Due to the MC4R-mediated protection of hippocampal neurons, the 12-day treatment of animals with Nle4,D-Phe7-α-MSH prevented the decrease of the spatial memory and the learning caused by ischemic stroke." (PMID 28031898, 2015).
multiple sclerosis (3 papers, 2025). A progressive autoimmune disorder affecting the central nervous system resulting in demyelination. "The observed effects in animal models suggest that MC4R agonists could be valuable as neuroprotective and neurodegenerative agents in various neurodegenerative diseases, addressing a significant unmet medical need, such as in multiple sclerosis (MS)." (PMID 41002740, 2025).
pancreatic cancer (3 papers, 2017 to 2021). "To address this hypothesis, we examined whether intracerebroventricular (ICV) infusion of agouti-related peptide (AgRP), an inverse agonist of the MC4R, improved appetite during the progression of pancreatic cancer cachexia." (PMID 33824339, 2021). "Similarly, in the pancreatic cancer data set, we found that the receptor MC4R was deleted in 21 samples." (PMID 28676692, 2017).
sarcopenia (3 papers, 2017 to 2025). Progressive decline in muscle mass due to aging which results in decreased functional capacity of muscles. "Recent trials have focused on the prevention of cancer-related sarcopenia, including exercise training, nutritional supplements like omega-3 fatty acids or medication-based concepts such as myostatin inhibitors or melanocortin-4 receptor antagonists." (PMID 28050694, 2017).
uremia (3 papers, 2009 to 2019). A clinical syndrome associated with the retention of renal waste products or uremic toxins in the blood. "Finally, other abnormalities as sex hormones, brain neurotransmitters or receptors acquired disorders in uremia (i.e., MC4-r), may contribute to the diversity of EBD in this population." (PMID 31191339, 2019).
attention deficit-hyperactivity disorder (2 papers, 2016 to 2023). A disorder characterized by a marked pattern of inattention and/or hyperactivity-impulsivity that is inconsistent with developmental level and clearly interferes with functioning in at least two settings (e.g. at home and at school). "This case report suggested a possible link between the MC4R deletion and attention deficit hyperactivity disorder (ADHD) because a number of individuals on the patient's father's side were reported to have ADHD." (PMID 27738543, 2016).